COPS5 (COP9 signalosome subunit 5)
Diseases named in the same sentence as COPS5 in open-access papers (continued):
Sharing a sentence is not in itself a finding about the gene and the disease.
tumor (continued). "It is also evident that overexpression of COPS5 is further enriched in tamoxifen-resistant tumours." (PMID 27375289, 2016). "However, knockdown of COPS5 by inducible shRNA restored the sensitivity to tamoxifen-treatment in the COPS5-overexpressed resistant tumours." (PMID 27375289, 2016). "The results showed that these epithelial and tumor cell lines exhibited a significant decrease in proliferation (P < 0.01, two-tailed Student’s t tests), providing further evidence for the important roles of COPS5 downregulation in the resistance of MPI cells to malignant transformation." (PMID 38360878, 2024). "In addition, the worse clinical outcomes are unlikely to be associated with tumour subtypes because COPS5 expression was similar in luminal A and B tumours." (PMID 27375289, 2016). "Furtherly, we characterized the antitumor efficacy of COPS5 knockdown in nude mice with EOC burden, which showed decreased tumor growth and cell proliferation under platinum treatment." (PMID 36135183, 2022). "In seven cases (UCHL1, USP9X, USP11, USP10, USP22, COPS5 and COPS6), dysregulation was observed in more than one tumor type." (PMID 21283576, 2011). "Despite the understanding of the COP9 signalosome subunit 5 (CSN5) in tumor genesis, there is no conclusive evidence on its value to predict the survival and prognosis of digestive system tumor patients." (PMID 35870903, 2022). "Because of the pivotal role of COPS5 for the COP9 signalosome in mammalian cells, this study primarily focused on COPS5 to investigate the possibility of coordinated expression of the COP9 subunits in the normal and tumor tissues." (PMID 27903243, 2016). "COPS5, which is overexpressed in HCC in an amplification‐ and ATF4‐dependent manner, stabilizes MK2 through deubiquitination and, in turn, induces HSPB1 activation, protecting HCC cells from ferroptosis and thus promoting sorafenib resistance and tumor progression." (PMID 40198582, 2025). "Consistent with our cellular studies, COPS5 KO reduced tumor growth and potentiated tumor growth suppression conferred by sorafenib in BALB/c nude mice bearing HepG2 subcutaneous xenografts, as detected by both tumor volume and weight, which could be offset by ferrostatin‐1 treatment." (PMID 40198582, 2025). "Interestingly, while knockdown of an essential gene PLK1 induced a remarkable growth inhibition of the subcutaneous tumours of parental MCF7 cells, neither knockdown nor overexpression of COPS5 showed a significant impact on MCF7 tumour growth." (PMID 27375289, 2016).
infection (7 papers, 2016 to 2025). The state of being infected such as from the introduction of a foreign agent such as serum, vaccine, antigenic substance or organism. "To test if overexpression of COPS5 plays a causative role in driving resistance to tamoxifen, we next established MCF7 cell lines stably expressing wild-type (WT) and metalloprotease-deficient D151N COPS5 (refs 20, 21) by lentiviral infection." (PMID 27375289, 2016).
neurodegenerative disease (4 papers, 2010 to 2022). A disorder of the central nervous system characterized by gradual and progressive loss of neural tissue and neurologic function. "APP/BIN1/COPS5 3xTg-AD mice are a suitable model for evaluating epigenetic changes in AD, the discovery of new epigenetic-related biomarkers for AD diagnosis, and new epidrugs for the treatment of this neurodegenerative disease." (PMID 35269588, 2022). "In addition, some CAMs have been shown to shuttle between FA and nucleus to regulate gene expression, including CDK5, ERK, GSK3B and COPS5 (JAB1) and members of the LIM family of proteins (PXN and Trip6), many of which have been implicated in the molecular pathology of neurodegenerative diseases." (PMID 22815752, 2012).
COPS5 also shares sentences with these, for which no sentence is quoted: non-small cell lung carcinoma (7 papers); Machado-Joseph disease (6); gastric cancer (5); Alzheimer disease (4); atherosclerosis (4); invasive breast carcinoma (4); triple-negative breast carcinoma (4); glioblastoma (3); myeloma (3); thyroid cancer (3); acute myeloid leukemia (2); Cerebral ischemia (2); congenital muscular dystrophy (2); diabetes (2); gallbladder cancer (2); Infertility (2); laryngeal squamous cell carcinoma (2); lymph node metastasis (2); myeloproliferative disease (2); neurological diseases (2); soft tissue sarcoma (2); Arthritis (1); astrocytoma (1); Atherosclerotic lesion (1); Atrophy (1); benign tumors (1); bladder cancers (1); cardiac hypertrophy (1); cholangiocarcinoma (1); Cognitive impairment (1).
A further 44 diseases each share a sentence with COPS5 in 1 paper.